BBS9 (Bardet-Biedl syndrome 9)
Diseases named in the same sentence as BBS9 in open-access papers:
BBS9 is named in the same sentence as 74 diseases in open-access papers, as found by Europe PMC text mining. Sharing a sentence is not in itself a finding about the gene and the disease. The quoted sentences say what the papers report.
Bardet-Biedl syndrome (28 papers, 2008 to 2025). A ciliopathy with multisystem involvement. "Ultimately, the presence of a pathogenic BBS9 variant in conjunction with the patient's clinical phenotype supports Bardet-Biedl Syndrome as the unifying diagnosis." (PMID 41333852, 2025). "Ultimately, the pathogenic BBS9 variant and clinical phenotype supported Bardet-Biedl Syndrome as the unifying diagnosis." (PMID 41333852, 2025). "In conclusion, we found a novel homozygous variant c.1114C>T in BBS9 of an autosomal recessive Bardet-Biedl syndrome family." (PMID 34692830, 2021). "On 7p14.3, rs6947352 is intronic to BBS9, which causes Bardet–Biedl syndrome when mutated, involving retinopathy and intellectual disability." (PMID 33723403, 2021). "In two siblings with Bardet‐Biedl syndrome, a deep‐intronic BBS9 (MIM *607968) homozygous variant (NC_000007.14:g.33346372C>T; NM_198428.2: c.1329+1738C>T) was recognized." (PMID 31736247, 2020). "In two brothers with Bardet‐Biedl syndrome, a deep‐intronic BBS9 homozygous variant, c.1329+1738C>T (transcript NM_198428.2), was recognized." (PMID 31736247, 2020). "Mutations of BBS9 are related with the Bardet-Biedl syndrome, a rare genetic disorder with highly variable symptoms." (PMID 30678657, 2019). "The current finding has increased the mutational spectrum of the Bardet Biedl Syndrome mutation in the Pakistani population and thereby will increase our knowledge to understand the potential role of the BBS9 protein in BBSome protein complex." (PMID 26846096, 2016). "In summary, our data represent the first BBS9 gene mutation being reported in a Pakistani family associated with Bardet Biedl syndrome." (PMID 26846096, 2016). "Despite these measures, she remained significantly symptomatic with persistent hyperphagia and recurrent urticaria until genetic testing identified a pathogenic variant in BBS9, supporting a diagnosis of Bardet-Biedl Syndrome and ultimately guiding initiation of setmelanotide therapy." (PMID 41333852, 2025). "Genetic testing later identified a pathogenic BBS9 variant, confirming Bardet-Biedl Syndrome." (PMID 41333852, 2025). "BBS9 has previously been associated with the Bardet-Biedl syndrome in human." (PMID 29121877, 2017). "Loss-of-function mutations in human BBS9 and other members of the BBSome cause Bardet-Biedl syndrome, associated with a series of clinical features including obesity, renal anomalies, and retinopathy, with the obese phenotype as one of the key features of Bardet-Biedl syndrome patients." (PMID 30231021, 2018). "In this case study, we describe an eight-year-old Saudi girl diagnosed with Bardet-Biedl syndrome (BBS), characterized by a rare homozygous mutation in the BBS9 gene." (PMID 39211725, 2024). "BBS9 and BBS10 have been reported as causative genes in Bardet–Biedl syndrome, and their proteins are thought to play a role in protein trafficking and the function of photoreceptors that connect cilia to outer segments." (PMID 37298549, 2023). "This gene is known also as BBS9 gene and recognized as one of the recent Bardet-Biedl syndrome genes." (PMID 20017981, 2009). "For example, the gene pair containing Akap1 (A kinase anchor protein 1), and Bbs9 (Bardet-Biedl syndrome 9) using Lin and Jiang methods score a similarity of 1.0." (PMID 18680592, 2008). "Although the exact function of the BBS9 gene has not yet been determined, mutations in this gene are known to cause Bardet-Biedl syndrome, another classic ciliopathy that can affect multiple systems and has a highly variable phenotype." (PMID 22912587, 2012). "Similarly, BBS9 is one of 14 genes known to be responsible for Bardet-Biedl syndrome, a multisystem disorder." (PMID 22912587, 2012).
Bardet-Biedl syndrome (continued). "Variants are reported for further clinical evaluation in the "potentially relevant variants" which means that this result might support a genetic etiology for the clinical presentation of our patient which concludes to diagnose our patient with Bardet-Biedl syndrome 9 (BBS9)." (PMID 36348931, 2022). "In Bardet–Biedl syndrome, TTC8, BBS9, WDPCP, and IFT27 were shared by the two pipelines, and BBS4, BBS7, BBS12, and IFT74 suffered significantly different selective pressures between TG and BG birds." (PMID 35456484, 2022). "In addition, heterozygous carriers of a mutant BBS allele in humans show increased levels of obesity, without showing any of the other Bardet-Biedl syndrome features, analogous to the observed phenotype in carriers of the BBS9 deletion." (PMID 30231021, 2018).
Obesity (8 papers, 2018 to 2025). Accumulation of substantial excess body fat. "Patients with BBS caused by homozygous or compound heterozygous mutations in BBS9 are characterized by obesity, polydactyly, renal anomalies, retinopathy and mental retardation." (PMID 31488071, 2019). "Two of the rare heterozygous nonsense variants identified (p.R75X and p.R481X) were found in BBS9 within one proband, suggesting that obesity is caused by compound heterozygosity." (PMID 31488071, 2019). "Interestingly, we show that the positive effect on growth is induced by a heterozygous loss-of-function of the BBS9 gene, associated with obesity in human and mouse." (PMID 30231021, 2018). "Mouse null-mutants in genes that form the BBSome complex have been associated with similar phenotypic features including obesity, lower birth weights, and partial embryonic lethality, again supporting the BBS9 role in increased growth rate, and the lower birth weight." (PMID 30231021, 2018). "A significant proportion of affected individuals carrying biallelic truncation variants in BBS9 shows primary signs of BBS (i.e., retinal dystrophy, bilateral polydactyly, obesity, ID/DD, and genitourinary and hepatic abnormalities)." (PMID 39125883, 2024). "BBS9 is a gene associated with Bardet-Biedel Syndrome (BBS), an autosomal recessive condition with multiple clinical features including renal abnormalities, obesity, and HTN." (PMID 38162683, 2023). "The heterozygous mutation NM_198428.3:c.(442+1_443-1)_(702+1_703-1)del in the BBS9 gene may not be considered pathogenic because the gene has only been shown to be involved in monogenic obesity in a recessive model." (PMID 37835041, 2023).
ciliopathies (7 papers, 2012 to 2025). "Using zebrafish as a model, we show that knockdown of bbs9 with specific antisense morpholinos leads to developmental abnormalities in retina and brain including hydrocephaly that are consistent with the core phenotypes observed in syndromic ciliopathies." (PMID 22479622, 2012).
craniosynostosis (3 papers, 2015 to 2022). Craniosynostosis is defined as the premature fusion of one or more cranial sutures leading to secondary distortion of skull shape resulting in skull deformities with a variable presentation. "The first GWAS on craniosynostosis identified susceptibility loci for non-syndromic sagittal craniosynostosis near bone morphogenetic protein-2 (BMP2) and within Bardet-Biedl syndrome 9 (BBS9)." (PMID 35451466, 2022).
Hyperglycemia (3 papers, 2020 to 2024). An increased concentration of glucose in the blood. "Recent association studies have suggested BBS9 to be associated with hyperglycaemia and insulin resistance." (PMID 39085583, 2024). "In our study, a strong correlation between hyperglycemia and insulin resistance and BBS9 gene variants was noted." (PMID 33138063, 2020). "A strong association between hyperglycemia and insulin resistance in patients and the presence of variants in BBS9 gene was observed." (PMID 33138063, 2020).
retinal degeneration (3 papers, 2012 to 2022). Degeneration of the retina. "The retinal degeneration in zebrafish, exhibited by bbs9-spMO morphants, is a further indication of cilia dysgenesis similar to the phenotype produced by Rpgr knockdown, which causes abnormal ciliary transport." (PMID 22479622, 2012). "Thus, for the three largest subgroups of patients BBS10 (20 patients), BBS1 (15 patients) and BBS9 (five patients) there is a similar pattern of retinal degeneration." (PMID 35886001, 2022).
Wilms tumor (3 papers, 2014 to 2022). An embryonal neoplasm characterized by the presence of epithelial, mesenchymal, and blastema components. "BBS9 gene is also associated with other disorders; the gene has been a candidate for Wilms' tumor and also has a strong association with primary ovarian insufficiency." (PMID 35222663, 2022).
ciliary dyskinesia (2 papers, 2012 to 2019). "Thus, the hydrocephaly in bbs9-spMO morphant could be attributed to ciliary dyskinesia." (PMID 22479622, 2012).
cone-rod dystrophy (2 papers, 2019 to 2022). Inherited retinal dystrophies that belong to the group of pigmentary retinopathies. "This mutation has previously been reported in a compound heterozygous state with a second BBS9 mutation, but in association with non-syndromic cone-rod dystrophy (CRD)." (PMID 31888296, 2019). "A total of 16 patients (26%) were found to have a cone or cone-rod dystrophy, but it appears to be distributed evenly between BBS subtypes (3/15 BBS1, 2/3 BBS2, 3/3 BBS3, 1/5 BBS9, 5/20 BBS10, and 2/3 BBS12)." (PMID 35886001, 2022).
Leber congenital amaurosis (2 papers, 2010 to 2024). Leber congenital amaurosis (LCA) is a retinal dystrophy defined by blindness and responses to electrophysiological stimulation (Ganzfeld electroretinogram (ERG)) below threshold, associated with severe visual impairment within the first year of life. "Genetic analysis with a single molecule molecular inversion probes-based panel that targets the exons and splice sites of 113 genes associated with retinitis pigmentosa and Leber congenital amaurosis revealed a homozygous rare missense variant in the BBS9 gene (c.263C>T;p.(Ser88Leu))." (PMID 38534779, 2024). "This strategy has been performed in BBS consanguineous families to detect new genes, such as BBS9, BBS11, and BBS12; in other retinal pathologies, such as Leber congenital amaurosis, this strategy allowed the identification of novel mutations in the LCA5 gene." (PMID 20142850, 2010).
Nystagmus (2 papers, 2022 to 2024). Rhythmic, involuntary oscillations of one or both eyes related to abnormality in fixation, conjugate gaze, or vestibular mechanisms. "Fourteen (70%) of the 20 BBS10 patients suffered from nystagmus, and 4/5 (80%) of the BBS9 patients but only 4/15 (27%) patients with BBS1." (PMID 35886001, 2022).
acute kidney injury (1 paper, 2019). Sudden and sustained deterioration of the kidney function characterized by decreased glomerular filtration rate, increased serum creatinine or oliguria. "We identified several potential loci, in particular PHLPP2, BBS9, RyR2, DUSP4 and HSPA8, associated with new-onset of atrial fibrillation, delirium, myocardial infarction, acute kidney injury and stroke after cardiac surgery." (PMID 30678657, 2019).
adenovirus infection (1 paper, 2019). "Persistent adenovirus infection of B-lymphocytes has been shown to significantly down-regulate several cellular genes (BBS9, BNIP3, BTG3, CXADR, SLFN11, and SPARCL -), however, none are reported to obviously function in the regulation of metabolism." (PMID 31864392, 2019).
Bull's eye maculopathy (1 paper, 2022). Progressive maculopathy characterized by concentric regions of hyper- and hypopigmentation, with an initial foveal sparing and whose appearance is said to resemble the central target of a dart board. "The BBS9 patient also exhibits a bull’s eye maculopathy, seen as a dark macula surrounded by paler rings in the AF images, in addition to hypoautofluorescent spots." (PMID 35886001, 2022).
cognitive decline (1 paper, 2024). "The early diagnosis and management of our patient also illuminate the potential benefits of timely intervention, particularly in mitigating some of the syndrome’s progressive aspects, such as vision loss, renal abnormalities specifically associated with BBS9, and cognitive decline." (PMID 39211725, 2024).
end-stage renal disease (1 paper, 2025). "In the present study, end-stage renal disease requiring dialysis was identified in one participant with BBS7-related BBS, one with BBS9-related BBS, and one with BBS1-related BBS." (PMID 40087798, 2025).
endometrial cancer (1 paper, 2023). Primary or metastatic malignant neoplasm involving the endometrium (mucous membrane that lines the endometrial cavity).
Hepatic steatosis (1 paper, 2022). Steatosis is a term used to denote lipid accumulation within hepatocytes. "In the proband, who also exhibited hepatic steatosis, an additional allele in BBS9 (p.(Met126Leu)) was found." (PMID 35835773, 2022).
hydrocephaly (1 paper, 2012). "Hydrocephaly in bbs9-spMO morphants suggested a possible ciliary abnormality in the ventricles and ependymal canal." (PMID 22479622, 2012).
leprosy (1 paper, 2016). Leprosy is a chronic infectious disease affecting primarily the skin and peripheral nervous system. "The SNP rs4720118 located in the eighteenth intron of BBS9 gene, which was significantly down regulated in the skin of leprosy patient." (PMID 27976721, 2016). "We confirmed all the known leprosy susceptibility loci and identified four novel loci on 3p25.2 (SYN2), 7p14.3 (BBS9), 8p23.1 (CTSB) and 8q24.11 (MED30)." (PMID 27976721, 2016).
lung adenocarcinoma (1 paper, 2024). A carcinoma that arises from the lung and is characterized by the presence of malignant glandular epithelial cells. "Circ_BBS9 has been identified as a tumor suppressor in lung adenocarcinoma (LUAD) and holds promise as a diagnostic biomarker." (PMID 39139574, 2024). "Subsequently, we analyzed the prognosis of 398 lung adenocarcinoma patients from the GEO database who expressed the BBS9 gene." (PMID 39139574, 2024).
neuroblastoma (1 paper, 2015). Neuroblastoma (NB) is the most common solid, extracranial childhood tumor. "Among the neuroblastoma genes, RAD54B, BBS9 and UNKL were detected in exosomes while BBS9, IGFN1 and PKD1L3 were identified in ectosomes." (PMID 25944692, 2015).
renal dysfunction (1 paper, 2019). "In contrast, some of the described genetic variants associated with complications after cardiac surgery, namely BBS9 in renal dysfunction, were found in our study." (PMID 30678657, 2019).
retinal disease (1 paper, 2014). "BBS9, MPP7, MED27, these three genes found here to interact with CFH have also been reported to be important for retinal disease." (PMID 24901472, 2014).
Stroke (1 paper, 2019). Sudden impairment of blood flow to a part of the brain due to occlusion or rupture of an artery to the brain. "For stroke, rs4098926, the SNP with the lowest p-value for this complication is located in the BBS9 gene." (PMID 30678657, 2019). "Additionally, the exact role of BBS9 in the pathogenesis of stroke after cardiac surgery has to be evaluated." (PMID 30678657, 2019).
vitiligo (1 paper, 2024). Generalized well circumscribed patches of leukoderma that are generally distributed over symmetric body locations and is due to autoimmune destruction of melanocytes. "In region 4: 62,791,008–63,734,743 pb, associated with vitiligo eyes, we identified two genes, the BBS9 (Bardet-Biedl syndrome 9) gene and the PR9 (PR9 pre-mRNA splicing factor) gene." (PMID 39199954, 2024).
tumor (3 papers, 2014 to 2024). "Circ_BBS9 acts as a tumor suppressor in LUAD and may serve as a potential diagnostic biomarker." (PMID 39139574, 2024). "We compared the expression levels of BBS9 in tumor tissues and adjacent normal tissues, revealing differential expression of circ_BBS9 in various tumor tissues." (PMID 39139574, 2024). "Furthermore, in different tumor grades, the expression of BBS9 was significantly lower in G2 and G3 compared to G1, suggesting a correlation between BBS9 and tumor grading." (PMID 39139574, 2024). "Furthermore, the observed decrease in circ_BBS9 expression corresponded with higher tumor grades, implying a potential correlation between reduced circ_BBS9 expression levels and an unfavorable prognosis in LUAD." (PMID 39139574, 2024). "Using data from the GEO database (GSE116959), we assessed the mRNA expression of BBS9 in LUAD tissues and non-tumor tissues and validated the protein-level expression of BBS9 in LUAD through the Human Protein Atlas (HPA)." (PMID 39139574, 2024).
cancer (2 papers, 2021 to 2025). A tumor composed of atypical neoplastic, often pleomorphic cells that invade other tissues. "These modules contained several cancer regulators such as Intraflagellar Transport (IFT) complex proteins (IFT74, IFT88), BBSome complex proteins (BBS2, BBS7, BBS9, BBS12), exocyst complex components (EXOC3, EXOC4, EXOC6B, EXOC7, and EXOC8), TTC8, TTC21B, EVC, and NEK1." (PMID 40700427, 2025).
infection (1 paper, 2025). The state of being infected such as from the introduction of a foreign agent such as serum, vaccine, antigenic substance or organism. "We previously reported that expression of several cellular genes, including CXADR, BNIP3, SPARCL1, SLFN11, BBS9 and BNIP3, is significantly downregulated by epigenetic means during the persistent phase of infection of B cells." (PMID 41497616, 2025).
Kidney disease (1 paper, 2025). "Kidney disease has been described as more prevalent in BBS2-, BBS7-, and BBS9-related BBS, as well as in BBS6-, BBS10-, and BBS12-related BBS." (PMID 40087798, 2025).
neurodegenerative disease (1 paper, 2025). A disorder of the central nervous system characterized by gradual and progressive loss of neural tissue and neurologic function.
BBS9 also shares sentences with these, for which no sentence is quoted: retinopathy (4 papers); Insulin resistance (3); behavioral disorders (2); genetic disease (2); Osteopenia (2); Retinal dystrophy (2); amyotrophic lateral sclerosis (1); asthma (1); atrial fibrillation (1); Autosomal Recessive Rod-Cone Dystrophy (1); Bartter syndrome (1); breast carcinoma (1); chronic obstructive pulmonary disease (1); Cornelia de Lange syndrome (1); Crohn disease (1); cyst (1); delirium (1); diaphanospondylodysostosis (1); DiGeorge syndrome (1); Down syndrome (1); Ehlers-Danlos syndrome (1); Fraser syndrome (1); genitopatellar syndrome (1); Hearing impairment (1); Hyperinsulinemia (1); hypogonadism (1); inflammatory bowel disease (1); liver failure (1); Megacystis (1); metastatic tumours (1).
A further 13 diseases each share a sentence with BBS9 in 1 paper.